ACTB (actin beta)
Diseases named in the same sentence as ACTB in open-access papers (continued):
Sharing a sentence is not in itself a finding about the gene and the disease.
liver cancer (8 papers, 2010 to 2025). An epithelial or non-epithelial malignant neoplasm that arises from the liver. "While many genes get high EGIS in specific cancer types, such as HSP90AA1 in pancreatic cancer, AKT1 in glioblastoma and pancreatic cancer, and ACTB in glioblastoma and liver cancer." (PMID 40478912, 2025). "We also examined the top most informative features and observed that the most informative nullomers were found at liver cancer-associated genes, including FTH1, EEF2, TMSB10, ACTB and the long non-coding RNA MALAT among others." (PMID 38351138, 2024). "ACTB plays important roles in renal cell carcinoma, colorectal cancer, liver cancer etc." (PMID 37691922, 2023). "In hepatic cancer cell lines, the first six stable reference genes were YWHAZ, ACTB, B2M, UBC, HPRT1, and RNA18S." (PMID 34752497, 2021). "CAP2 was coexpressed with TP53BP2, ENA/VASP in the liver cancer, and CFL1, CFL2, DSTN, ACTB, ACTG1, and ROBO1." (PMID 28423713, 2017). "Moreover, in hepatic cancer cell lines including Huh7, HepG2, and PLC-PRF5, ACTB, HPRT1, UBC, B2M, and YWHAZ were among the first six stable genes ranked by geNorm, NormFinder, and RefFinder algorithm." (PMID 34752497, 2021). "Similarly, a panel of five reference genes, namely ACTB, HPRT1, UBC, YWHAZ, and B2M is also recommended for RT-qPCR data normalization of three hepatic cancer cell lines, including Huh7, HepG2, and PLC-PRF5." (PMID 34752497, 2021). "Besides that, a panel of five nominees, including ACTB, HPRT1, UBC, YWHAZ, and B2M showed higher stability than others in hepatic cancer cell lines." (PMID 34752497, 2021). "However, higher expression of ACTB and B2M was reported in stomach tissues than AGS/SNU-638 stomach cancer cell lines as well as higher B2M expression in liver tissues than HepG2/Hep3B/SK-HEP-1/SNU-182 liver cancer cell lines." (PMID 20507635, 2010). "Moreover, for the studied cell lines, it is proposed that not to use ACTB and B2M; and TBP for normalizing the breast and hepatic cancer cell lines derived RT-qPCR data, respectively." (PMID 34752497, 2021).
viral infection (8 papers, 2012 to 2024). "We only observed small differences in H2A.Z loading at ISG promoters following virus infection, similar to the effects observed on the constitutively active ACTB promoter." (PMID 38940561, 2024). "Cell lysates were collected and probed with anti- Flag antibody to detect exogenous Flag-labelled ATG4A as well as anti-VP1 and anti-ACTB as viral infection and loading controls, respectively." (PMID 36146840, 2022). "To test whether nuclear transcript poly(A) tail lengths are significantly affected by virus infection, we analyzed poly(A) tails of abundant host transcript ACTB using the Affimetrix USB poly(A) tail-length assay kit." (PMID 38629840, 2024). "Low PFN1, CFN1, and ACTB levels in individuals with low adjusted seroconversion might indicate a recent viral infection (prior to receiving the vaccine) which weakened the immune response." (PMID 36366577, 2022). "It is possible that despite its abundance, ACTB is not representative of the nuclear host transcripts with alterations in their polyadenylation due to virus infection." (PMID 38629840, 2024). "However, ACTB and GAPDH remain widely used in the studies of host gene response to virus infections, including influenza viruses." (PMID 23043930, 2012). "As expected, the PA-X-deficient virus did not cause significant downregulation of ACTB and G6PD transcripts compared to mock-infected cells, and the decrease in POLR2A and MALAT1 transcript was weaker although not significantly different from the WT virus infection." (PMID 38629840, 2024).
colorectal cancer (7 papers, 2015 to 2023). A primary or metastatic malignant neoplasm that affects the colon or rectum. "Our subgroup analysis also showed that whether ACTB was used as a reference also affected the diagnostic efficacy of SDC2 methylation for colorectal cancer." (PMID 35754025, 2022). "Ct values for mSEPT9 and ACTB were within the same range for colorectal cancer, prostate, lung, breast, and melanoma cancer cell lines." (PMID 35992328, 2022). "Furthermore, ACTB goes hand in hand with many cancers and plays a major role in lung and colorectal cancer, and so on." (PMID 30781701, 2019). "Some data indicated a role of β- and γ-actins in carcinogenesis: components of the Arp2/3 complex were up-regulated in colorectal cancers, increased ACTG1 and reduced ACTB levels were identified in osteosarcoma analysis." (PMID 26008973, 2015).
diabetes (7 papers, 2014 to 2026). "In total, 5/9 individuals with the ACTB (p.Ser348Leu) variant had neonatal diabetes or hyperglycaemia." (PMID 42107907, 2026). "The present study aims to explore whether the common variants at the ACTB gene contribute to diabetic kidney disease (DKD) susceptibility in patients with type 2 diabetes mellitus (T2DM)." (PMID 31396261, 2019). "Intensity of ACTB expression at six months of diabetes showed a downward trend compared to the control group (P = 0.07)." (PMID 37462767, 2023). "Next, the relationship between ACTB methylation and the clinical characteristics (including smoking, alcohol drinking, hypertension, diabetes, and blood lipid levels) of 272 controls and 281 CHD cases was investigated." (PMID 36061541, 2022). "In consistent with our findings, it has been reported that ACTB is one of the most unstable genes in mouse models of obesity and diabetes and that the ACTB expression in the hypothalamus and intestine from an obese rat model is markedly altered with changes in energy status." (PMID 33330591, 2020). "Our results indicated that blood–based ACTB methylation was inversely correlated with the level of HDL–C, but not the levels of LDL–C, TC, and TG, or the status of smoking, drinking, hypertension, and diabetes." (PMID 36061541, 2022). "There was no or weak correlation between ACTB methylation and the other blood lipid indexes (levels of LDL–C, TC, TG), as well as the status of smoking, drinking, hypertension, and diabetes." (PMID 36061541, 2022).
hepatocellular carcinoma (7 papers, 2007 to 2025). A malignant tumor that arises from hepatocytes. "Some qPCR studies on hepatocellular carcinoma (HCC) used GAPDH or ACTB for normalization." (PMID 17640361, 2007). "In an in vivo murine cancer model studied by Northern blot analysis, all three HKGs, i.e., ACTB, PPIA, and GAPDH, were found to be significantly upregulated in hepatoma cells compared to adjacent normal liver tissue." (PMID 40943534, 2025). "In addition, KEGG analysis indicated the involvement of apoptotic pathways, including “platinum drug resistance,” “hepatocellular carcinoma,” “thyroid hormone signaling pathway,” and “amyotrophic lateral sclerosis”, as highlighted by the decreased expression of A0A0S2Z3C5 (BCL2L1) and P60709 (ACTB)." (PMID 39562369, 2025).
bladder cancer (6 papers, 2016 to 2025). "Most disulfidoptosis genes were downregulated in multiple cancer types, including PDLIM1, TLN1, and MYH10 in lung squamous cell carcinoma (LUSC), MYL6 and DSTN in prostate adenocarcinoma (PRAD), and FLNA and ACTB in bladder cancer (BLCA)." (PMID 38862242, 2024). "ANOVA indicated that ACTB and GAPDH were differentially expressed among the diagnostic groups such as bladder cancer stage and grade." (PMID 30214686, 2018). "Likewise, we have observed that ACTB gene was unstable in bladder cancer cell lines exposed to hypoxia." (PMID 27835695, 2016). "(A) Relative enrichment of circHIPK3 levels or ACTB mRNA between IP and input for the three RNA-binding proteins (RBPs) GRWD1, IGF2BP1, and IGF2BP2 in the bladder cancer cell line FL3." (PMID 39041323, 2024). "Bladder cancer marker candidates as well as reference genes (ACTB, GAPDH, ALDOB) were assayed by RT-qPCR in 254 urine samples including 173 bladder cancer patient urine samples." (PMID 30214686, 2018). "We also found that the expression levels of exosomal lncRNA-UCA1 in the serum of bladder cancer patients were markedly higher than that in healthy control subjects, and the expression levels of exosomal lncRNA-UCA1 were normalized to ACTB (β-actin) or GAPDH." (PMID 28841829, 2017). "Accordingly, seven of the most commonly used reference genes (ACTB, GAPDH, HPRT, B2M, SDHA, TBP, and 18S) were amplified in the three bladder cancer cell lines exposed to normoxia and hypoxia." (PMID 27835695, 2016).
gastric cancer (6 papers, 2010 to 2024). A primary or metastatic malignant neoplasm involving the stomach. "The literature confirmed that 18S had good linearity and stability compared with the reference genes glyceraldehyde 3-phosphate dehydrogenase, U6 small nuclear RNA (U6), β-actin (ACTB), and tubulin (TUB) in gastric cancer." (PMID 34222007, 2021). "ACTB and GAPDH showed most abundant expression in both 'stomach cancer cell lines' and 'non-stomach cancer cell lines', but in contrast HPRT1 showed lowest expression level." (PMID 20507635, 2010). "The stability analyses by geNorm suggest B2M-GAPDH, as best reference gene combination for 'stomach cancer cell lines'; RPL29-HPRT1, for 'all stomach tissues'; and ACTB-18S rRNA, for 'all stomach cell lines and tissues'." (PMID 20507635, 2010). "For 'stomach cancer cell lines,' the higher V4/5 (0.018) and V5/6 (0.028) values than V2/3 or V3/4 explain why the high-scoring HPRT1 and ACTB genes should be excluded." (PMID 20507635, 2010).
Alzheimer disease (5 papers, 2021 to 2023). A progressive, neurodegenerative disease characterized by loss of function and death of nerve cells in several areas of the brain leading to loss of cognitive function such as memory and language. "In recent research, hypoxia-induced miR-210 was shown to target synaptic function genes (GRINA, TMUB1, and AP2S1), plasticity genes (ACTB), Alzheimer’s disease genes (APOE), and genes implicated in MAPK/VEGF and OXPHOS signaling pathways." (PMID 35626359, 2022). "Association of APOE, EGFR, and ACTB SNPs with Alzheimer’s disease under logistic regression analysis." (PMID 34956307, 2021).
breast tumor (5 papers, 2010 to 2025). "To test this hypothesis, first we investigated the expression of Giantin in circulating breast tumor cells (n = 1448) compared to a housekeeping gene (ACTB)." (PMID 37068117, 2023). "ACTB was verified as one of the best combination genes for breast tumor and normal tissues." (PMID 25617865, 2015). "The expression of six HKs (TFRC, GUSB, GAPDH, ACTB, HPRT1 and RPLP0) was investigated using geNorm and NormFinder softwares in forty breast tumor, four normal and eight adjacent tissues." (PMID 21702980, 2011). "The first dataset includes relative expression levels of 6 reference genes (ACTB, GAPDH, MRPL19, PSMC4, PUM1, and SF3A1) quantified in 80 breast tumor samples." (PMID 20470420, 2010).
diabetic kidney disease (5 papers, 2019 to 2023). Progressive kidney disorder caused by vascular damage to the glomerular capillaries, in patients with diabetes mellitus. "Besides, it has shown that the ACTB gene variants can increases the susceptibility of the Han Chinese population to diabetic kidney disease." (PMID 33960101, 2022). "A previous study speculated that the ACTB gene could play a role in epithelial-to-mesenchymal transition (EMT)-induced diabetic kidney disease (DKD)." (PMID 37833721, 2023).
glioblastoma (5 papers, 2017 to 2025). The most malignant astrocytic tumor (WHO grade IV). "Furthermore, Vazquez-Blomquist investigated 18S and 28S gene stability in comparison to that of ACTB and GAPDH in glioblastoma-derived cells." (PMID 37568514, 2023).
Lissencephaly (5 papers, 2015 to 2025). A spectrum of malformations of cortical development caused by insufficient neuronal migration that subsumes the terms agyria, pachygyria and subcortical band heterotopia. "The genetic factors known to cause lissencephaly are DCX (double cortin), gene TUBA1A (tubulin alpha 1a), ACTB (actin beta), ACTG1 (actin gamma 1), and ARX (aristaless-related homeobox)." (PMID 39040723, 2024).
microcephaly (5 papers, 2015 to 2025). A congenital or acquired developmental disorder in which the circumference of the head is smaller than normal for the person's age and sex. "Mutations in the ACTB and ACTG1 genes, encoding the ubiquitous beta- and gamma-cytoskeletal actin isoforms, respectively, cause a broad spectrum of neurodevelopmental disorders, with microcephaly as the most frequent one." (PMID 41372632, 2025). "Taken together, ACTB haploinsufficiency could represent a single upstream defect that simultaneously perturbs neural network formation and somatic growth, thereby unifying the neurodevelopmental delay, microcephaly, and short stature into a coherent pathophysiological framework." (PMID 41141068, 2025).
schizophrenia (5 papers, 2011 to 2018). A major psychotic disorder characterized by abnormalities in the perception or expression of reality. "Given its pleiotropic nature, reduction of ACTB in schizophrenia may have a range of causes and consequences." (PMID 22675524, 2012). "Thus, alcohol use and a diagnosis of schizophrenia were both associated with decreased ACTB mRNA." (PMID 22675524, 2012). "ACTB expression was reduced in schizophrenia (ANOVA P = 0.016; planned contrast scz<con P = 0.005) and bipolar disorder (planned contrast bip<con P = 0.008) compared to controls." (PMID 22675524, 2012). "ACTB, CKB, NEFL, INA and GFAP had link to both schizophrenia and depression, while CTSD, HSPA8, NEFM and TUBA1A had link to schizophrenia." (PMID 23272063, 2012). "These genes included SBNO2, CEACAM5, AKAP1, UBC, ACTB, UBB, and FOS for schizophrenia; SEC24C, PGLYRP1, ARHGAP4, RPL22, SLC6A11, and SYK for bipolar disorder; and SRRT, PARK2, LILRA4, STK17A, IGFBP2, and NF1 for major depression." (PMID 22373040, 2011). "The top ranked genes in centrality analysis, UBC, ACTB, and UBB, were all abnormally expressed in schizophrenia samples." (PMID 22373040, 2011). "RT-PCR confirmed reductions of MBP, ACTB and TB10, but not MOG or SCG10, in schizophrenia." (PMID 22675524, 2012).
acute myocardial infarction (4 papers, 2013 to 2025). Necrosis of the myocardium, as a result of interruption of the blood supply to the area. "A prior study further implicated ACTB in acute myocardial infarction (AMI) susceptibility, though the precise mechanistic basis remains undefined." (PMID 40672380, 2025). "GAPDH, GNAS, and ACTB were shown to be the most stable genes in platelets of healthy individuals, while HDGF, GNAS, and ACTB were the most stable in platelets of patients with the history of myocardial infarction." (PMID 23389042, 2013). "We found GAPDH, GNAS, and ACTB to be the best combination of reference genes for platelet transcript level studies in healthy individuals, while HDGF, GNAS, and ACTB are the best for studies in patients with the history of myocardial infarction." (PMID 23389042, 2013). "Our results indicate that GAPDH, GNAS, and ACTB are the most stable genes expressed in platelets of healthy individuals and HDGF, GNAS, and ACTB were identified as the most stable reference genes expressed in platelets from patients with the history of myocardial infarction." (PMID 23389042, 2013).
asthma (4 papers, 2011 to 2025). "In conclusion, our findings provide evidence for the differential involvement of actin cytoskeletal isoforms in the regulation of ASM contraction and their association with AHR in asthma, identifying ACTB and ACTA2 as a key determinant in the disease’s pathophysiology." (PMID 40980809, 2025). "Within this context, our findings suggest that ACTG1 and ACTB play interdependent roles in regulating AHR in asthma." (PMID 40980809, 2025). "Proteomic analysis confirmed these proteins in guinea pig tracheal smooth muscle, although expression changes differed from the bronchus, except for ACTB, which increased in the asthma model." (PMID 40980809, 2025). "However, given that previous studies have reported stable ACTB expression as a control marker in various molecular biology techniques, the increased expression of ACTB was unexpected in asthma model guinea pigs." (PMID 40980809, 2025). "Based on immunohistochemistry data, the interactomes related to the expression of MYH11, MYL9, ACTG1, ACTA2, ACTB, TAGLN, and FLNA in the bronchial smooth muscle of guinea pigs in an asthma model were generated." (PMID 40980809, 2025). "This study confirmed the expression of peptides corresponding to ACTA2, ACTB, ACTG1, MYH11, FLNA, MYL9, and TAGLN in both control guinea pigs and the asthma model." (PMID 40980809, 2025). "In asthma model guinea pigs, ACTG1 expression significantly decreased compared to controls, while the expression levels of ACTB, ACTA2, and MYL9 significantly increased (p < 0.01, n = 5, each group)." (PMID 40980809, 2025). "ACTG1 exhibits a differential behavior compared to ACTB and ACTA2 in the present study, as its decrease correlates with AHR in asthma." (PMID 40980809, 2025). "It is possible that the reduction of ACTG1 in asthma may promote the upregulation of ACTA2, and probably ACTB, thereby enhancing AHR through the activation of inhibitory pathways that prevent muscle relaxation, such as those regulated by ROCK." (PMID 40980809, 2025). "Thus, this study demonstrated that the expression of the main smooth muscle actins, namely, ACTA2, ACTB, and ACTG1, was modified in the bronchial smooth muscle—a crucial tissue in asthma —of guinea pigs in an asthma model." (PMID 40980809, 2025). "It has been reported that GAPDH and ACTB were not suitable as RGs for quantitative analysis of gene expression in asthma, which has similar pathophysiology to CRS26." (PMID 29371606, 2018).
autism (4 papers, 2012 to 2023). Persistent deficits in social interaction and communication and interaction as well as a markedly restricted repertoire of activity and interest as well as repetitive patterns of behavior. "In contrast to our findings indicating ACTB as an unsuitable internal control for RT-qPCR analysis in childhood autism, the study by Garbett and colleagues gives ACTB a high praise as a reference gene for transcriptome analysis in postmortem brain tissue samples from ASD patients." (PMID 27754318, 2016).
colon carcinoma (4 papers, 2017 to 2022). "Previous studies showed that the mRNA level of ACTB was down-regulated in esophageal cancer, colon cancer, and LUSC compared to normal tissues." (PMID 36232605, 2022).
E. coli infection (4 papers, 2015 to 2023). "However RRMS clinic subtype patients also show an increase in the ACTB, KRT18, FYN, TUBA4A, NCL, CTNNB1 proteins which are a part of pathogenic E. coli infection pathway, which induce the mobilization of inflammatory cells." (PMID 25942430, 2015).
epilepsy (4 papers, 2016 to 2025). A brain disorder characterized by episodes of abnormally increased neuronal discharge resulting in transient episodes of sensory or motor neurological dysfunction, or psychic dysfunction. "Variants in the ACTB gene may disrupt its interaction with these genes to cause the phenotypes of neurodevelopmental disorders and epilepsy." (PMID 40677923, 2025). "The enrichment analysis revealed the vital roles of ACTB in epilepsy/neurodevelopment." (PMID 40677923, 2025).